RNU6-282P (RNA, U6 small nuclear 282, pseudogene)
Gene: Small nuclear RNA gene on chromosome 2 (48,501,922 to 48,502,024, reverse strand). Ensembl gene ENSG00000202227.
Homologues: Orthologues: chimpanzee U6 (97% identical), macaque U6 (88% identical), dog U6 (83% identical). Paralogues in human: RNU6-1145P (86% identical), RNU6-116P (86% identical), RNU6-38P (86% identical), RNU6-832P (86% identical), RNU6-10P (85% identical), RNU6-15P (85% identical), RNU6-25P (85% identical), RNU6-29P (85% identical), RNU6-310P (85% identical), RNU6-33P (85% identical), RNU6-379P (85% identical), RNU6-41P (85% identical), and 1289 more.